RBM47 (RNA binding motif protein 47)
Description:
Single-stranded RNA-binding protein that functions in a variety of RNA processes, including alternative splicing, RNA stabilization, and RNA editing. Functions as an enzyme-substrate adapter for the cytidine deaminase APOBEC1. With APOBEC1 forms an mRNA editing complex involved into cytidine to uridine editing of a variety of mRNA molecules. Through the binding of their 3'UTR, also stabilizes a variety of mRNAs and regulates the expression of genes such as the interferon alpha/beta receptor and interleukin-10. Also involved in the alternative splicing of several genes including TJP1. Binds the pre-mRNA (U)GCAUG consensus sequences in downstream intronic regions of alternative exons, regulating their exclusion and inclusion into mRNAs. Independently of its RNA-binding activity, could negatively regulate MAVS by promoting its lysosomal degradation (By similarity).
Synonyms: FLJ20273; NET18
Tractability: PROTAC: ubiquitination databases record sites on it; its protein half-life has been measured.
Gene: Protein-coding gene on chromosome 4 (40,423,267 to 40,630,892, reverse strand). Ensembl gene ENSG00000163694.
Subcellular location: Nucleus; Cytoplasm
Subcellular location (Human Protein Atlas): Cytosol; Nucleoplasm
Gene Ontology:
Molecular function: enzyme binding; enzyme-substrate adaptor activity; mRNA 3'-UTR binding; protein binding; RNA binding; mRNA binding; nucleic acid binding
Biological process: 3'-UTR-mediated mRNA stabilization; cytidine to uridine editing; positive regulation of type I interferon-mediated signaling pathway; regulation of alternative mRNA splicing, via spliceosome; positive regulation of interleukin-10 production
Cellular component: apolipoprotein B mRNA editing enzyme complex; cytoplasm; nucleus
Genetic constraint (gnomAD): Loss-of-function variants: 20 observed, 43.88 expected, observed/expected ratio (o/e) 0.46, 90% interval 0.32 to 0.66. The upper end of that interval is the gene's LOEUF score, 0.66, which puts it in group 2 of 6, group 1 being the genes least tolerant of losing a copy. Missense variants: 674 observed, 840.55 expected, observed/expected ratio (o/e) 0.8, 90% interval 0.75 to 0.86. Synonymous variants: 361 observed, 351.35 expected, observed/expected ratio (o/e) 1.03, 90% interval 0.94 to 1.12.
Homologues: Orthologues: chimpanzee RBM47 (99% identical), macaque RBM47 (99% identical), guinea pig RBM47 (96% identical), rabbit RBM47 (95% identical), dog RBM47 (94% identical), mouse Rbm47 (94% identical), rat Rbm47 (94% identical), pig RBM47 (86% identical), tropical clawed frog rbm47 (85% identical), zebrafish rbm47 (78% identical). Paralogues in human: A1CF (49% identical), RBM46 (44% identical), DND1 (18% identical), RBM19 (14% identical), HNRNPA3 (13% identical), RBMX (13% identical), HNRNPA1 (13% identical), HNRNPA2B1 (13% identical), RBMXL1 (13% identical), RBM4 (12% identical), HNRNPA1L2 (12% identical), HNRNPA1L3 (12% identical), and 24 more.
Diseases named in the same sentence as RBM47 in open-access papers:
RBM47 is named in the same sentence as 63 diseases in open-access papers, as found by Europe PMC text mining. Sharing a sentence is not in itself a finding about the gene and the disease. The quoted sentences say what the papers report.
breast cancer (19 papers, 2014 to 2026). A primary or metastatic malignant neoplasm involving the breast. "RBM47 is significantly downregulated in claudin-low and basal breast cancers with heterozygous or homozygous loss of functions and during lung and brain metastasis." (PMID 35831298, 2022). "Low RBM47 expression is significantly associated with a poor prognosis in two subtypes of claudin-low breast cancer and basal breast cancer." (PMID 36052258, 2022). "Through integrative analysis of clinical breast cancer gene expression datasets, cell line models and mutation data from cancer genome resequencing studies, RBM47 was identified as a suppressor of breast cancer progression and metastasis." (PMID 33845831, 2021). "RNA binding motif protein 47 (RBM47) was identified as a suppressor of breast cancer metastasis through analysis of clinical breast cancer gene expression datasets, cell line models, and mutation data." (PMID 31737791, 2019). "We found that low RBM47 expression was significantly associated with claudin-low and basal breast cancers, two subtypes of poor prognosis." (PMID 24898756, 2014). "Furthermore, analysis of the data from the TCGA cohort revealed that in basal breast cancer, RBM47 was targeted by a mutation or homozygous deletion in ∼8% of the cases." (PMID 24898756, 2014). "Epithelial specific alternative splicing is regulated by RBM47 that is also found inactive in some breast cancers and whose low expression in patients correlates with poor clinical outcome." (PMID 36707502, 2023). "RBM47 increases the stability of Dkk1 mRNA in breast cancer cells through direct binding to the noncoding region at the 3’ end of Dkk1 mRNA." (PMID 36052258, 2022). "For example, RNA-binding motif protein 47 (RBM47) can suppress progression and metastasis in breast cancer cells." (PMID 35985767, 2022). "The RNA binding motif protein 47 (RBM47) inhibited breast cancer metastasis by regulating DKK1 expression via Wnt pathway." (PMID 30819235, 2019). "As this mutation was already present in a minority subpopulation of the corresponding primary tumor, we looked for additional evidence of genetic RBM47 aberrations in primary breast cancer cohorts." (PMID 24898756, 2014). "We find that RBM47 binds robustly to ∼2500 gene transcripts in human breast cancer cells, with only a subset showing steady state level change or alternative splicing upon RBM47 reintroduction." (PMID 24898756, 2014). "Our work identifies RBM47 as an RNA-binding protein that can suppress breast cancer progression and demonstrates how the inactivation of a broadly targeted RNA chaperone enables selection of a pro-metastatic state." (PMID 24898756, 2014). "We further characterized the expression patterns of RBM47 in the TCGA cohort of 748 breast cancer samples studied by RNA-seq." (PMID 24898756, 2014). "This approach identified RNA binding motif protein 47 (RBM47) as a suppressor of breast cancer progression." (PMID 24898756, 2014). "As predicted by our results in WT6 and WT10 cells, knockdown of RBM47 in two additional breast cancer cell lines expressing high levels of endogenous RBM47, SKBR3 and ZR-75-30, reduced DKK1 mRNA levels." (PMID 24898756, 2014). "We have studied one such gene, the previously uncharacterized RBM47, and demonstrate that it has tumor suppressive functions in breast cancer." (PMID 24898756, 2014). "The induction of RBM47 by doxycycline was able to significantly delay the emergence of mammary tumors, and the tumors that formed were smaller in size." (PMID 24898756, 2014). "Thereby, RBM47 suppresses breast cancer progression and metastasis." (PMID 41335176, 2025). "In addition, the inhibitory effects of RBM47 was previously reported in the development of non-small cell lung cancer, breast cancer, and hepatocellular carcinoma." (PMID 39741300, 2024). "More importantly, GSE58380 dataset analysis indicated that RBM47 could bind to the 3′-untranslated region (UTR) of PDIA6 mRNA in breast cancer cells." (PMID 39741300, 2024).
breast cancer (continued). "Functionally, RBM47 was first identified as a tumor suppressor in breast cancer." (PMID 35831298, 2022). "RBM47 as a suppressor of breast cancer progression and metastasis." (PMID 34804951, 2021). "Through integrative analysis of clinical breast cancer gene expression datasets, cell line models of breast cancer progression, and mutation data from cancer genome resequencing studies, we identified RNA binding motif protein 47 (RBM47) as a suppressor of breast cancer progression and metastasis." (PMID 24898756, 2014). "The fact that RBM47 was able to increase DKK1 secretion therefore suggested that RBM47 may also inhibit Wnt signaling and consequently reduce the tumorigenic fitness of metastatic breast cancer cells." (PMID 24898756, 2014). "However, switching off the RBM47 gene in breast cancer cells had the opposite effect; these cells invaded the lungs of mice more efficiently." (PMID 24898756, 2014). "Indeed, even though RBM47 loss was associated with metastatic cancer clones in our model systems, evidence for selection against RBM47 was detected already in primary breast cancers." (PMID 24898756, 2014). "This validated RBM47 as a modulator of DKK1 mRNA level in breast cancer cells." (PMID 24898756, 2014). "RBM47 has been identified as a suppressor of breast cancer progression and metastasis, and patients with a low level of RBM47 tended to have a poor clinical outcome, which suppresses the metastasis of breast cancer by stabilizing transcripts of Dickkopf Wnt signaling pathway inhibitor." (PMID 33224957, 2020). "Some RBPs, such as lin28, RBM47, RNPC1, and HuR, have been found to have the ability to regulate breast cancer metastasis." (PMID 38783078, 2024). "RBM47, PCBP3, FRG1, SRP72 and other RBPs might regulate AS of ITGA6, ADGRE5, TNC and other genes and affect the EMT process of breast cancer cells." (PMID 38783078, 2024). "It was found in our study that RBM47, PCBP3, FRG1, SRP72 and other RBPs may regulate the AS of ITGA6, ADGRE5, TNC and other genes and affect the EMT process of breast cancer cells." (PMID 38783078, 2024). "Given the important role of RBM47 in progression of breast cancer, and similar structure, function between RBM47 and A1CF, we hypothesize that A1CF (-8aa) or A1CF may also play a biological role in breast cancer." (PMID 27231908, 2016). "By establishing the correlation network of differential RBPs and differential AS events, we found that RBM47, PCBP3, FRG1, SRP72, RBMS3 and other RBPs may regulate the AS of ITGA6, ADGRE5, TNC, COL6A3 and other cell adhesion genes, which may affect the EMT process of breast cancer cells." (PMID 38783078, 2024).
colorectal cancer (11 papers, 2017 to 2026). A primary or metastatic malignant neoplasm that affects the colon or rectum. "Down-regulation of the RNA-binding motif protein 47 (RBM47) frequently occurs in colorectal cancer (CRC) and is associated with poor prognosis." (PMID 41681975, 2026). "Public databases revealed stage-specific reduction in RBM47 expression in colorectal cancer associated independently with decreased overall survival." (PMID 37014710, 2023). "By analyzing mouse models and patient collections we could show that down-regulation of RBM47 promotes colorectal cancer metastasis and is associated with poor survival of CRC patients." (PMID 28680090, 2017). "Among the identified epithelial cell state-associated factors, down-regulation of the RBM47 (RNA binding motif protein 47) mRNA displayed the most significant association with metastasis and poor survival in multiple cohorts of colorectal cancer (CRC) patients." (PMID 28680090, 2017). "The gene encoding the RNA-binding motif protein 47 (RBM47) is highly expressed in epithelial cells and its down-regulation is characteristic for many types of cancer, among them colorectal cancer (CRC)." (PMID 41335176, 2025). "Recently, RBM47 has been proven to be a tumor suppressor for colorectal cancer (CRC) and lung cancer." (PMID 37962768, 2023). "RBM47 mRNA was decreased in human colorectal cancer versus paired normal tissue, along with alternative splicing of tight junction protein 1 mRNA." (PMID 37014710, 2023). "Previous study had shown the downregulation of RBM47 could promote colorectal cancer progression through EMT." (PMID 37962768, 2023). "In addition, we found reduced expression of RBM47 in samples of human colorectal cancer compared with paired normal tissue, and databases revealed decreased overall survival with low RBM47 expression." (PMID 37014710, 2023). "Furthermore, as an RNA-binding protein, it is worth exploring whether the regulatory effects of RBM47 may differ between left-sided and right-sided colorectal cancer due to the different primary sites." (PMID 40695891, 2025). "Moreover, the depletion of RBM47 led to the downregulation of epithelial-associated genes including OCLN, CDH1, TJP1, and CLDN1 with a concomitant enhancement in cell migration, mesenchymal markers, invasion and metastasis in colorectal cancer, which was consistent with our report." (PMID 35831298, 2022). "RBM47 has been shown to inhibit the progression of several malignancies, including thyroid carcinoma, nasopharyngeal carcinoma, lung cancer and colorectal cancer, whereas its role in PCa has not been characterized." (PMID 37559353, 2023).
nasopharyngeal carcinoma (7 papers, 2021 to 2026). A carcinoma arising from the nasopharyngeal epithelium. "RBM47 deficiency was found to relieve proliferation, migration, and tumorigenesis of nasopharyngeal carcinoma cells whereas its overexpression showed the exact opposite trend." (PMID 39741300, 2024). "verified the inhibitory effect of RBM47 knockdown on proliferation of nasopharyngeal carcinoma cells." (PMID 39741300, 2024). "RBM47, as a transcription factor and selective splicing regulator, promoted the development of nasopharyngeal carcinoma through various pathways." (PMID 37962768, 2023). "Conversely, other studies have suggested that RBM47 may exhibit oncogenic properties in nasopharyngeal carcinoma via its role as a DNA/RNA-binding protein." (PMID 38914961, 2024). "However, in nasopharyngeal carcinoma, RBM47 presented oncogenic effects on tumor behaviors by acting as a DNA/RNA binding protein." (PMID 35831298, 2022). "However, it is worth noting that RBM47 may present malignant significance on nasopharyngeal carcinoma and non-small cell lung cancer survival." (PMID 38914961, 2024).
colon cancer (6 papers, 2021 to 2025). "We have previously shown that RBM47 mRNA expression is significantly lower in tumors when compared to adjacent normal colon tissue by analyzing The Cancer Genome Atlas (TCGA) colon cancer patient cohort representing 39 matched tumor/normal tissue pairs." (PMID 41335176, 2025). "Those latter studies, reflecting work in cancer cell lines, support an emerging consensus that RBM47 likely functions as a tumor suppressor in both breast and colon cancer, with a role in cancer metastasis." (PMID 37014710, 2023). "The here observed RBM47 downregulation in CMS4 colon cancers is in agreement with a previous report on its decreased protein expression during EMT in association with metastasis in a cohort of primary CRCs." (PMID 36346211, 2022). "Like RBM47, FOXA1 is highly expressed in normal colon epithelial cells, but significantly down-regulated in colon cancers." (PMID 41335176, 2025). "Like RBM47, FOXA1 expression was consistently and significantly down-regulated in colon cancers when compared to adjacent normal colon tissue." (PMID 41335176, 2025). "Furthermore, we explored a potential link between the expression level of RBM47 and MSI/MSS status of our cohort comprising 17 dMMR and 101 pMMR-colon cancers." (PMID 38914961, 2024).
hepatocellular carcinoma (6 papers, 2021 to 2026). A malignant tumor that arises from hepatocytes. "Our results demonstrated a consistent positive correlation between LINC00862 and RBM47 mRNA within the hepatoma cell lines." (PMID 41487470, 2026). "To validate the correlation between in vitro expression of LINC00862 and RBM47, we employed qRT-PCR to assess the expression levels of RBM47 mRNA across 5 hepatoma cell lines." (PMID 41487470, 2026). "The results indicated that the RBM47 protein was concurrently located in both the nucleus and cytoplasm in subcutaneously implanted tumor tissue and hepatoma cells." (PMID 35831298, 2022). "Firstly, we examined the expression of RBM47 in different hepatoma cell lines by qRT-PCR and noticed that RBM47 presented higher expression in Huh7 cells and lower expression in HCCLM3 cells." (PMID 35831298, 2022). "Our data revealed a significant up-regulation of LINC00862 by RBM47 in hepatoma cells." (PMID 41487470, 2026). "Taken together, miR-122 could promote metastasis of hepatoma cells by regulating RBM47-ITGAV-TGF-β signaling." (PMID 40638600, 2025). "We then observed tumor metastasis in the lungs by in vivo fluorescent imaging and discovered that RBM47 overexpression could significantly reduce hepatoma cell metastasis in vivo." (PMID 35831298, 2022). "RBM47 expression resulted in an increased rate of apoptosis in hepatoma cells." (PMID 35831298, 2022). "For instance, RNA-binding protein Nova1 and NELFE promote cancer growth in hepatocellular carcinoma (HCC) cells, whereas RBM47 and RBM43 have been shown to suppress HCC growth." (PMID 34434291, 2021). "In hepatocellular carcinoma (HCC), RBM47 upregulation significantly inhibits tumor progression in vitro, primarily through the upregulation of UPF1, serving as a tumor suppressor by acting as a DNA/RNA binding protein at both transcriptional and post-transcriptional levels." (PMID 39659787, 2024).
lung carcinoma (6 papers, 2020 to 2023). "Other mechanisms of RBM47-mediated tumor inhibition in lung cancer have also been reported, RBM47 plays a tumor-suppressive role in lung cancer through inhibiting Nrf2 activity." (PMID 33224957, 2020). "Reduced levels of RBM47 have also been observed in non–small cell lung cancer (NSCLC) patients, which correspond to a poorer prognosis and more advanced disease." (PMID 33224957, 2020). "For instance, RBM47 regulated TJP1 alternative splicing to promote lung cancer EMT transition." (PMID 37660095, 2023). "Therefore, converging with previous studies on the implication of ISGylation or RBM47 in lung cancer, it is plausible to propose that RBM47-ISGylation exerts tumor suppressor functions through its pleiotropic effects in activating antitumor immunity within the pulmonary microenvironment." (PMID 38036512, 2023). "Hence, our findings demonstrate that site-specific RBM47-ISGylation mediated by a chimeric E3 ligase diminishes TSC22D3 expression in various cell types, such as immune cells and human lung cancer cells." (PMID 38036512, 2023). "Our findings demonstrate that RBM47-ISGylation inhibits the expression of TSC22D3 in human cells, including lung cancer cell lines and the T lymphocyte line Jurkat, demonstrating that human RBM47-ISGylation has a consistent function, as confirmed by mouse models." (PMID 38036512, 2023).
papillary thyroid carcinoma (6 papers, 2022 to 2026). "However, RBM47 was found to be downregulated in thyroid carcinoma and its overexpression inhibited proliferation of papillary thyroid carcinoma cells." (PMID 39741300, 2024). "A recent study showed that RBM47 inhibited proliferation in papillary thyroid carcinoma by stabilizing the lncRNA SNHG5, which in turn acted as a scaffold, binding with USP21 to regulate the expression of FOXO3, implying that USP21 is required for the tumor-suppressive role of RBM47." (PMID 35846989, 2022). "In papillary thyroid carcinoma, SNHG5 binds and stabilizes RBM47, preventing ubiquitin-mediated degradation of FOXO3 via recruitment of USP21." (PMID 41550840, 2026). "Likewise, RBM47/SNH5G signaling was found to stabilize FOXO3A and promote its translocation into nucleus, which activated autophagy and inhibited the cell proliferation of papillary thyroid carcinoma (PTC)." (PMID 38326905, 2024).